CMTM5 (CKLF like MARVEL transmembrane domain containing 5)
Diseases named in the same sentence as CMTM5 in open-access papers (continued):
Sharing a sentence is not in itself a finding about the gene and the disease.
tumor (18 papers, 2015 to 2025). "CMTM5 gene encodes a chemokine superfamily member, encoding a protein with tumor suppressor effects." (PMID 39166861, 2024). "CMTM5 is a member of the CMTM protein family that has been associated with regulating tumor immunity, including CMTM5 itself." (PMID 35274615, 2022). "Gene methylation is the underlying mechanism of CMTM5, as promoter methylation could silence CMTM5, and the restoration of CMTM5 overexpression can activate the apoptosis pathway to induce tumor cell death." (PMID 38223763, 2024). "In this study, CMTM3 was highly expressed in ESCA, and was closely related to the tumor stage, while CMTM5 was lowly expressed in tumor tissue." (PMID 40179060, 2025). "CMTM5 overexpression has a significant inhibitory effect on the formation of tumor cell line colonies." (PMID 38223763, 2024). "For instance, CMTM5 has a tumor inhibitory function, an immune system modulation capability, and an active role in the male reproductive system." (PMID 35176183, 2022). "Limited clinical evidence of the direct tumor suppressor functions of CMTM5, CMTM7 and CMTM8 has been presented to date." (PMID 32944388, 2020). "Located on chromosome 14 at position 14q11.2, an important locus associated with the pathogenesis of multiple carcinomas 24-27, CMTM5 also exhibits potential tumor suppressor activities, similar to TM4SF." (PMID 32328181, 2020). "Overexpression of CMTM5 significantly inhibited Huh7 cell growth and metastasis in vitro and inhibited xenograft tumor growth in vivo." (PMID 33282744, 2020). "Similarity to the CMTM3 gene, the promoter methylation of CMTM5 gene is the main mechanism of tumor evading anticancer effect." (PMID 33282744, 2020). "CMTM5 also encodes a protein that potentially has a four transmembrane-helix architecture, which provides a theoretical basis for the new tumor suppressor gene of CMTM5." (PMID 31998718, 2019). "In vivo experiment results suggested that the tumour growth was significantly suppressed in CMTM5 overexpressed group but significantly promoted in mimics group." (PMID 29691981, 2018). "In this study, we also found that restoring CMTM5 expression in Huh7 cells not only significantly suppressed tumour proliferation, promoted cell apoptosis, but also inhibited cell metastasis and invasion in vitro." (PMID 29213215, 2017). "In conclusion, our study provided the first evidence of the reduced expression and the tumor suppressor role of CMTM5 in HCC through regulating PI3K-AKT signalling." (PMID 29213215, 2017). "The only gene disconnected from this block at T3 was CMTM5—a gene belonging to the chemokine-like factor gene superfamily with putative tumor suppressor activity." (PMID 25938420, 2015). "Previous studies have identified CMTM5 as a tumor suppressor in several cancers." (PMID 39166861, 2024). "CMTM5 has tumor suppressor activity but is frequently inactivated by promoter methylation." (PMID 38223763, 2024). "CMTM5 overexpression inhibited tumor volume and weight in nude mice." (PMID 39166861, 2024). "In vivo and In vitro studies proved that CMTM5 could suppress tumor growth by regulating P13K-AKT signaling." (PMID 35252165, 2022). "By far, CMTM5 exhibits tumor suppressor activity in different types of cancer." (PMID 33282744, 2020). "A novel tumor suppressor CKLF-like MARVEL transmembrane domain-containing member 5(CMTM5) has a MARVEL domain and may regulate transmembrane signaling." (PMID 32328181, 2020). "The results presented in this study are the first demonstration that CMTM5 loss and EGFR deregulation are observed in PCa cells, which provides a crucial signaling platform required for androgen-independent tumor transition and progression and for the malignant behavior of tumor cells." (PMID 32328181, 2020). "CMTM5 is a well-characterized tumor suppressor that may related to many types of cancer and to the development and progression of PCa 26, 28-35, 37-39." (PMID 32328181, 2020).
tumor (continued). "Additionally, overexpression of CMTM5 also significantly suppressed xenograft tumour growth in vivo." (PMID 29213215, 2017). "Overexpression of CMTM5 also suppressed xenograft tumour growth in vivo in a HCC xenograft model." (PMID 29213215, 2017). "Human chemokine like factor (CKLF)-like MAL and related proteins for vesicle trafficking transmembrane, domain-containing member 5 (CMTM5) has been shown to involved and may function as a tumour suppressor in tumorigenesis." (PMID 29213215, 2017). "Collectively, our findings indicate that CMTM5 may function as a tumour suppressor in HCC carcinogenesis." (PMID 29213215, 2017). "Our data suggest that CMTM5 might function as a tumour suppressor in human HCC, and represent a valuable potential therapeutic target for HCC." (PMID 29213215, 2017). "CMTM5 and CMTM7 are both members of the CMTM family, and studies have shown that both in vitro and in vivo experiments demonstrated that knockdown of CMTM7 enhanced tumor growth by impairing autophagy, indicating that CMTM5 may participate in tumor development by mediating autophagy." (PMID 39166861, 2024). "Thus, CMTM5 is involved in several signaling pathways related to tumorigenesis and may be a potential target for tumor therapy." (PMID 38223763, 2024). "The results suggested that miR‐10b‐3p could promote tumour growth by suppressing CMTM5 In vivo." (PMID 29691981, 2018). "Our findings demonstrate that CMTM5 might act as a putative tumour suppressor in HCC." (PMID 29213215, 2017). "The top 5 overexpressed proteins in tumor compared to NT (ranked according to the log2(FC) T vs CT) included SFRP2, KDM5A, CMTM5, HSPA5 and FN1." (PMID 39681068, 2024). "MTSS1 and CMTM5 are tumor suppressor genes, although in some cancer types, MTSS1 was identified as a tumor enhancer." (PMID 34390367, 2021). "Multivariate analysis indicated that tumour size (P = 0.011), vascular invasion (P = 0.033), TNM stage (P = 0.009) and CMTM5 expression (P = 0.013) were independent prognostic factors for overall survival in patients with HCC." (PMID 29213215, 2017). "For example, we did not rule out whether CMTM5 can affect other forms of tumor cell death, such as apoptosis, and autophagy." (PMID 39166861, 2024). "Moreover, our study found that lower levels of CMTM5 expression were related to lower RFS in luminal A and basal-like subtypes, but not in luminal B and HER2+ subtype, which indicated that this was also present with tumor heterogeneity in the CMTM5 expression." (PMID 31998718, 2019).
cancer (12 papers, 2014 to 2025). A tumor composed of atypical neoplastic, often pleomorphic cells that invade other tissues. "A previous study indicated that CMTM5-v1, the major expressed mRNA splicing variant of CMTM5, contains 156 amino acids and is broadly expressed in human fetal and adult tissues but is frequently epigenetically silenced by promoter methylation in cells derived from various cancers." (PMID 32328181, 2020). "CMTM3, CMTM4, and CMTM5 are thought to bring about favorable prognostic factors in several cancer types." (PMID 35252165, 2022). "Our previous study revealed that CMTM5 expression is significantly reduced or undetectable in PCa tissues and several cancer cells compared with BPH tissues." (PMID 32328181, 2020). "The role of CMTM5 has been investigated in many human cancer types, such as cervical, pancreatic, ovarian, hepatocellular carcinoma and leukemia 29-34." (PMID 32328181, 2020). "Previous studies showed that CMTM family genes CMTM3 and CMTM5 are silenced or down-regulated by promoter CpG methylation in several carcinoma cell lines and primary tumors." (PMID 24586462, 2014). "CMTM5 is widely expressed in normal tissues and its expression levels are either downregulated or silenced in liver, kidney, and prostate cancers." (PMID 31998718, 2019). "On the contrary, negative LASSO coefficients were found for the genes ADRB2, CRYAB, NR4A1, CMTM5, ZBTB16, SYNE3, and RAD51, which were downregulated in cancer compared with normal samples." (PMID 36552262, 2022). "Unlike other CMTM family members, CMTM5 is localized separately on 14q11.2, a locus frequently altered in many types of cancers." (PMID 31998718, 2019).
cardiovascular disease (1 paper, 2020). "CMTM5 has been implicated in platelet aspirin responses through studies in cardiovascular disease." (PMID 32318053, 2020).
hematological malignancies (1 paper, 2022). "This significant female predominance in CMTM5 downregulation was not suggested by other studies on CMTM5 expression in hematological or non‐hematological malignancies." (PMID 35176183, 2022).
CMTM5 also shares sentences with these, for which no sentence is quoted: myeloid leukemia (2 papers); ovarian carcinoma (2); pancreatic cancer (2); gastric cancer (1); multiple sclerosis (1).